RNU6-156P (RNA, U6 small nuclear 156, pseudogene)
Gene: Small nuclear RNA gene on chromosome 9 (40,759,600 to 40,759,706, reverse strand). Ensembl gene ENSG00000278331.
Homologues: Orthologues: chimpanzee U6 (97% identical), macaque U6 (92% identical), dog U6 (64% identical), rabbit U6 (64% identical), pig U6 (62% identical), rabbit U6 (60% identical). Paralogues in human: RNU6-1293P (100% identical), RNU6-458P (97% identical), U6 (97% identical), RNU6-1132P (96% identical), RNU6-614P (96% identical), RNU6-721P (95% identical), U6 (95% identical), RNU6-1207P (93% identical), RNU6-811P (93% identical), RNU6-978P (93% identical), RNU6-452P (88% identical), RNU6-666P (87% identical), and 1287 more.